RBX1 (ring-box 1)
Diseases named in the same sentence as RBX1 in open-access papers (continued):
Sharing a sentence is not in itself a finding about the gene and the disease.
ovarian carcinoma (5 papers, 2014 to 2022). A malignant neoplasm originating from the surface ovarian epithelium. "To confirm that the pharmacological effects of MLN4924 were due to disrupting CRL4s, we silenced RBX1 (ROC1) and CUL4A, the core component of CRL complexes, in ovarian cancer A2780 and ES-2 cells." (PMID 35864225, 2022). "Moreover, we recently demonstrated that reduced expression of SKP1, CUL1 and RBX1 prevents Cyclin E1 degradation leading to an increase in abundance that induces CIN and promotes cellular transformation in colorectal and ovarian cancer contexts." (PMID 35008511, 2021). "It has been shown that underexpression of RBX1, due to gene CNL, might interfere with the KEAP1/CUL3/RBX1 complex, which also displays a E3 ubiquitin-ligase activity in thyroid and ovarian cancer." (PMID 25298778, 2014). "While the magnitude and frequency of KEAP1/CUL3/RBX1 complex component disruption were more prominent in the cohort we assessed, these results reveal the potential importance of alternative mechanisms of NRF2 activation in ovarian cancer and warrant consideration in future studies." (PMID 25114896, 2014).
COVID-19 (4 papers, 2021 to 2025). A disease caused by infection with severe acute respiratory syndrome coronavirus 2. "One example is the expansion of platelets in severe COVID-19 samples, comprising CRBN/RBX1-high (M33) and IFITM3-high (M34) subpopulations." (PMID 41066207, 2025). "From the PBMCs of influenza- and COVID-19–infected patients, MSC identified 2 platelet subpopulations expanded in patients with severe COVID-19—namely, CRBN/RBX1-high (M33) and IFITM3-high (M34) cells." (PMID 41066207, 2025). "One example is the expansion of platelets in severe COVID-19 samples, comprised of CRBN/RBX1-high (M33) and IFITM3-high (M34) subpopulations." (PMID 39764102, 2024). "From the PBMC of influenza and COVID-19 infected patients, MSC identified two platelet subpopulations expanded in severe COVID-19 patients, namely, CRBN/RBX1-high (M33) and IFITM3-high (M34) cells." (PMID 39764102, 2024).
lung adenocarcinoma (4 papers, 2020 to 2021). A carcinoma that arises from the lung and is characterized by the presence of malignant glandular epithelial cells. "In lung adenocarcinoma, MiR-378 and MiR-1827 also regulate the growth and invasion of cancer cells by targeting RBX1." (PMID 34281459, 2021). "To examine the correlation of UBE2F and RBX1 expressions in clinical samples of human lung adenocarcinoma, we collected a total of 20 lung adenocarcinoma tissues and performed a direct immunoblotting analysis to determine the protein levels of UBE2F and RBX1." (PMID 33184273, 2020). "We observed a reduction in RBX1 expression is in parallel with an increase in UBE2F expression in lung adenocarcinoma tissues." (PMID 33184273, 2020). "However, in human lung adenocarcinoma, miR‐378 promoted cancer cell invasion by targeting RBX1." (PMID 33372356, 2021). "Using the Pearson correlation methods, we found that the protein levels of UBE2F vs. RBX1 exerted a significantly negative correlation in 20 lung adenocarcinoma samples (Pearson R = −0.52, P = 0.019)." (PMID 33184273, 2020).
renal cell carcinoma (4 papers, 2014 to 2025). "CUL1 is a scaffold protein of the ubiquitin E3 ligase Skp1/Cullin1/Rbx1/F-box protein complex, which increased in renal cell carcinoma and promotes cancer cell proliferation, migration, and invasion." (PMID 31086232, 2019). "Genes such as TCEB2, HIF1A, TCEB1, CUL2, and RBX1 were involved in both of the first and the third routes of the renal cell carcinoma pathway." (PMID 25091575, 2014). "TCEB2, HIF1A, TCEB1, CUL2, and RBX1 were involved in the renal cell carcinoma pathway, while TCEB2, HIF1A, TCEB1, and CUL2 had the highest degree in the PPI network." (PMID 25091575, 2014). "Among the protein–protein interaction network, TCEB2, HIF1A, TCEB1, CUL2, RBX1, and PHF17 were hub genes which might be involved in the development of renal cell carcinoma." (PMID 25091575, 2014).
melanoma (3 papers, 2018 to 2025). A malignant, usually aggressive tumor composed of atypical, neoplastic melanocytes. "Loss of either CUL3, FBXL6, or RBX1 expression conferred a growth advantage in the presence of vemurafenib, indicating that an unimpaired SCF complex is critical for vemurafenib sensitivity in melanoma." (PMID 29880484, 2018).
osteosarcoma (3 papers, 2017 to 2024). A usually aggressive malignant bone-forming mesenchymal neoplasm, predominantly affecting adolescents and young adults. "Recently, we found that CUL4B was overexpressed in osteosarcoma and that the activated CUL4B formed an E3 ligase with DDB1, RBX1, and DCAF11, which further ubiquitinated p21 and caused p21 degradation, resulting in the disruption of cell cycle progression." (PMID 29377600, 2018). "Our recent study suggests that CUL4B associates with DDB1, RBX1, and DCAF11 to form a unique CRL4BDCAF11 E3 complex in human osteosarcoma cells, and this E3 ligase can specifically target p21Cip1 for degradation, thereby regulating cell cycle progression." (PMID 29377600, 2018). "Here, we demonstrated that CUL4B forms an E3 ligase with RBX1 (RING-box 1), DDB1 (DNA damage binding protein 1), and DCAF11 (DDB1 and CUL4 associated factor 11) in human osteosarcoma cells." (PMID 28446751, 2017). "A study found that in human osteosarcoma cells, CUL4B forms an E3 ligase with RBX1 (RING-box 1), DDB1 (DNA damage binding protein 1), and DCAF11 (DDB1 and CUL4 associated factor 11)." (PMID 39062505, 2024). "To illuminate the molecular function of CUL4B, especially to determine interacting proteins and to identify the substrates of CRL4B E3 ligase in osteosarcoma cells, we first confirmed interactions between CUL4B and RBX1 or DDB1 in vivo and in vitro." (PMID 28446751, 2017). "In summary, our results demonstrate that CUL4B forms an E3 ligase with RBX1, DDB1 and DCAF11 to recognize p21 as a substrate in human osteosarcoma cells." (PMID 28446751, 2017). "To determine whether CUL4B can interact with RBX1 and DDB1 in osteosarcoma cells, we first constructed the pCDNA3-CUL4B-Flag vector, which we then transfected into hFOB1.19, U2OS and Saos-2 cells." (PMID 28446751, 2017). "In addition, the same amount of CUL4B-Flag protein pulled down much more DDB1 and RBX1 protein in U2OS and Saos-2 osteosarcoma cells than in hFOB1.19 cells, suggesting that DDB1 and RBX1 are also upregulated in osteosarcoma cells." (PMID 28446751, 2017).
virus infection (3 papers, 2016 to 2022). "We first validated the initially observed interactions between NSP1 and Rbx1, Cul1, Cul3 and β-TrCP by co-immunoprecipitation (IP) of transiently overexpressed NSP1s, Rbx1 and Cul3 and in the context of virus infection." (PMID 27706223, 2016).
autoimmune disorders (2 papers, 2022 to 2023). "To verify the functional relationship between neddylation and CRLs in Treg cells, we compare the degree of autoimmune disorders and transcriptional alterations caused by Ube2m&Ube2f versus Rbx1&Sag deficiency in Treg cells." (PMID 37600496, 2023). "Double deletion of neddylation E2s Ube2m&Ube2f or E3s Rbx1&Sag in Treg cells leads to the impairment of suppressive function of Treg cells and results in severe autoimmune disorders, fully demonstrating the pivotal role of the neddylation-CRL axis in the maintenance of Treg cell fitness." (PMID 37600496, 2023). "The finding that mice of Rbx1 Treg deletion suffer from much more severe autoimmune disorders with much earlier fatality than those of Ube2m Treg deletion is unexpected, since Ube2m is an upstream E2, whereas Rbx1 is a downstream co-E3 in the neddylation cascade." (PMID 35641500, 2022).
bladder cancer (2 papers, 2021 to 2023). "RBX1 is widely reported to be associated with poor clinical prognosis and is highly expressed in many cancers, including bladder cancer." (PMID 37497216, 2023).
colitis (2 papers, 2022 to 2023). Inflammation of the colon. "If mice develop the colitis in 4 weeks, induced by co-injected naive conventional CD4+ T cells, it would indicate that Treg cells from Rbx1-deficient mice have lost suppression function, and vice versa." (PMID 35641500, 2022).
depression (2 papers, 2021 to 2024). "The top three genes of the module, YOD1, RBX1, and LEPR, have been shown previously to be associated with neurodegenerative diseases, bipolar disorder, and depression." (PMID 38726387, 2024). "For example, the RBX1 gene was reported as a significant contributor to both depression and ADs." (PMID 34566951, 2021).
glioblastoma (2 papers, 2021 to 2023). The most malignant astrocytic tumor (WHO grade IV). "Conversely, copy number gains (gains plus amplifications) for SKP1, CUL1, and RBX1 range from 3% (uterine) to 31% (liver), 12% (cervical) to 80% (glioblastoma), and 1% (prostate) to 22% (head and neck), respectively." (PMID 34445249, 2021). "Collectively, SKP1 copy number losses (shallow and deep deletions) range from 7% to 44% in prostate and ovarian cancers, respectively, while CUL1 and RBX1 losses range from 2% (glioblastoma) to 23% (head and neck) and 10% (prostate) to 80% (ovarian), respectively." (PMID 34445249, 2021). "The most significant phenotype was observed for U373 cells and we further delineated the effects of RBX1, ASH2L, SSRP1 ablation on glioblastoma cell fitness using this cell line." (PMID 37974198, 2023).
hepatocellular carcinoma (2 papers, 2021 to 2023). A malignant tumor that arises from hepatocytes. "Rbx1 is also associated with the antitumor DMC that can improve the immune microenvironment of hepatocellular carcinoma cells." (PMID 33919822, 2021). "RING box protein-1 (RBX1), also named ROC1, is an important RING component of CRL and overactivated in hepatocellular carcinomas connected with poor prognosis." (PMID 37771770, 2023).
HIV-1 infection (2 papers, 2017 to 2023). The type species of lentivirus and the etiologic agent of acquired immunodeficiency syndrome (AIDS). "The HIV Vpx/CUL4/DCAF1/RBX1 complex relieves inhibition of HIV-1 infection of macrophages by mediating SAMHD1 protein degradation." (PMID 38005838, 2023).
non-small cell lung carcinoma (2 papers, 2016 to 2020). A group of at least three distinct histological types of lung cancer, including non-small cell squamous cell carcinoma, adenocarcinoma, and large cell carcinoma. "Our recent study showed that both RBX1 and SAG/RBX2 are overexpressed in human non-small cell lung carcinomas." (PMID 27955654, 2016). "Both cisplatin and carboplatin treatments in A549 and H1299, two human non-small cell lung cancer cell lines, led to the obvious accumulation of UBE2F in a dose-dependent manner, but not other neddylation components (e.g., E1: NAE1 and UBA3; E2: UBE2M; E3: RBX1 and RBX2)." (PMID 33184273, 2020).
Serous Ovarian Cancer (2 papers, 2014 to 2022). "Roc1b homolog RBX1 in human has been reported to play a role in high-grade serous ovarian cancer (HGSOC) in women." (PMID 36056003, 2022).
thyroid (2 papers, 2014 to 2023). "Immunoblotting indicated that the expression of RBX1 in the ATC cell lines was markedly higher compared with that in the PTC and thyroid cell lines." (PMID 36810109, 2023).
adenoma (1 paper, 2023). A neoplasm arising from the epithelium. "Next, we measured potential accumulation of direct substrates of Rbx1 in hyperplasia/adenomas tissues with focused on few substrates, known to act as the tumor suppressors." (PMID 37470067, 2023).
colon cancer (1 paper, 2023). "(A, D, G, J) Keap1, DDB2, WSB2, or Rbx1 siRNAs were transiently transfected into human colon cancer cell line HCT-116 cells." (PMID 37943017, 2023).
colorectal cancer (1 paper, 2025). A primary or metastatic malignant neoplasm that affects the colon or rectum. "The demethylase enzymes of RNA m6A ALKBH5 and CRL1 were connected by circular RNA circAFF2 in colorectal cancer, indicating a direct connection with Rbx1, since RBX1 is a RING component of CRL1." (PMID 40642056, 2025).
Hyperglycemia (1 paper, 2024). An increased concentration of glucose in the blood. "Additionally, the hyperglycemia of flies expressing CUL1 in the whole body and HSD flies were rescued by UBA3, UBE2M, or RBX1 knockdown." (PMID 38212312, 2024).
leukemia (1 paper, 2021). A malignant (clonal) hematologic disorder, involving hematopoietic stem cells and characterized by the presence of primitive or atypical myeloid or lymphoid cells in the bone marrow and the blood. "NEDD8 and RBX1 inhibition by the small molecule inhibitor pevonedistat inhibited leukemia cell growth." (PMID 34857808, 2021).
lung squamous cell carcinoma (1 paper, 2014). "The frequency of disruption for ovarian tumors was comparable to the high frequencies observed in uterine carcinoma and lung squamous cell carcinoma (LUSC), where disruption of the KEAP1/CUL3/RBX1 E3-ubiquitin ligase complex is well established." (PMID 25114896, 2014).
lymphoma (1 paper, 2023). A malignant (clonal) proliferation of B- lymphocytes or T- lymphocytes which involves the lymph nodes, bone marrow and/or extranodal sites. "The decreased level of RBX1 was also associated with an increased level of p27 in adhered RPMI8226 cells and U266 cells and LY-8 lymphoma cells." (PMID 37639640, 2023). "Similarly, shRNA targeting RBX1 induced significantly less growth inhibition and cell death than the shControl transfected controls in the MM cells and lymphoma cell line." (PMID 37639640, 2023).
malaria (1 paper, 2024). Malaria is a serious and sometimes fatal disease caused by a parasite that commonly infects a certain type of mosquito which feeds on humans. "To investigate the CRLs of human malaria parasite Plasmodium falciparum, we generated parasites expressing tagged P. falciparum cullin-1 (PfCullin-1), cullin-2 (PfCullin-2), Rbx1 (PfRbx1) and Skp1 (PfSkp1)." (PMID 38416790, 2024). "al. in a recent study performed extensive immunoprecipitation of Rbx1, Skp1 and FBXO1 of the mouse malaria parasite P. berghei, and proposed that these proteins form an SCF in P. berghei." (PMID 38416790, 2024).
myopia (1 paper, 2022). "Of all the key nodes, Rbx1 ranked first, suggesting it plays an important role in the formation of form‐deprivation myopia." (PMID 34841657, 2022).
pancreatic cancer (1 paper, 2022). "Moreover, correlation analysis revealed that the mRNA levels of NEDD8 and NAE1, Ubc12, and Rbx1 had a statistically significant association with pancreatic cancer." (PMID 35155257, 2022). "Further Kaplan–Meier analysis indicated that patients with high mRNA levels of Rbx1 had worse overall survival than those with low expression in pancreatic cancer." (PMID 35155257, 2022). "Consistent with the upregulation of mRNA expression levels, the protein expression levels of Ubc12 and Rbx1 were higher in pancreatic cancer tissues than in adjacent normal tissues." (PMID 35155257, 2022). "Ubc12, Rbx1, and NEDD8 mRNA expression in pancreatic cancer tissues was notably higher than that in normal pancreatic tissues (p < 0.05)." (PMID 35155257, 2022).
renal carcinoma (1 paper, 2022). A carcinoma arising from the epithelium of the renal parenchyma or the renal pelvis. "To validate the differences of RBX1/2 expression, we analysed transcriptional expression of these both genes in various tumor cell lines of four common types of cancer (breast, lung, colorectal and renal cancer) and normal cells." (PMID 36059474, 2022).
renal tumour (1 paper, 2017). "CNAs of suppressor genes present in at least 5 renal tumour genomes linked PPP3CC, PPP2CB and RBX1 in 9/11/7 HRO tumours with 19/11/11 KEGG pathways." (PMID 28486536, 2017).
serous ovarian tumors (1 paper, 2014). "In conclusion, we have identified an extremely high frequency of genetic disruption affecting the KEAP1/CUL3/RBX1 E3-ubiquitin ligase complex in serous ovarian tumors, occurring predominantly through copy-number loss of RBX1." (PMID 25114896, 2014).
T-cell deficiency (1 paper, 2022). "Studies indicated that RBX1 expression are associated with the immune suppressive function of Treg cells, and T-cell deficiency, and RBX2 could trigger a series of immune responses, suggesting they may play important roles in regulating immune cells." (PMID 36059474, 2022).
cancer (41 papers, 2009 to 2025). A tumor composed of atypical neoplastic, often pleomorphic cells that invade other tissues. "We also conducted the co-expression analysis to further explore the association between RBX1/2 expression and immune checkpoints in pan-cancer using the TCGA database." (PMID 36059474, 2022). "We investigated RBX1/2 expression patterns and the association with clinicopathological features, and survivals of cancer patients obtained from the TCGA pan-cancer data." (PMID 36059474, 2022). "MiRNAs have been implicated in the deregulation of CRL2pVHL components in cancer; one example involves the downregulation of hsa-miR-194 in gastric cancer, which leads to RBX1 upregulation and subsequent increases in invasiveness." (PMID 35664333, 2022). "Patient-based data from The Cancer Genome Atlas (TCGA) provides further evidence supporting the possibility that aberrant expression and/or function of the core SCF complex components (SKP1, CUL1, and RBX1) have pathogenic roles in cancer." (PMID 34445249, 2021). "Previous studies reported that RBX1 is overexpressed in several human cancers and associates with poor prognosis of cancer patients." (PMID 33504946, 2021). "We also showed that RBX1 is overexpressed in a number of human cancers, and siRNA silencing of RBX1 caused cancer cell death as a result of sequential induction of G2-M arrest, senescence and apoptosis." (PMID 19660140, 2009). "Furthermore, we investigated the association with RBX1/2 expression and immune subtypes in the TCGA pan-cancer data, illustrating that the expression of RBX1 was lowest in the C3 immune subtype, while RBX2 was lowest in the C5 immune subtype." (PMID 36059474, 2022). "Beyond somatic mutations, SKP1, CUL1, and RBX1 gene copy number alterations including deep deletions (loss of 2 alleles), shallow deletions (loss of 1 allele), gains (gain of 1 allele), and amplifications (gain of ≥2 alleles) are frequently observed in all 12 cancer types." (PMID 34445249, 2021). "Recently, it has been shown that RBX1 is a major regulator of the ubiquitin–proteasome system (UPS) in cancer." (PMID 36810109, 2023). "Increasing evidence has shown that RBX1 expression promotes tumor progression and metastasis in several cancers, including non-small cell lung, liver, breast, ovarian, and bladder cancers." (PMID 36810109, 2023). "In summary, our results revealed that the important role of Ring finger members in the SCF complex, and the expression profile of RBX1/2 in pan-cancer." (PMID 36059474, 2022). "RBX1 silencing can inhibit cancer cell growth by inducing apoptosis, cell cycle arrest at G2-M phase and senescence." (PMID 35880551, 2022). "We also observed the significant correlation between RBX1/2 expression and the pathological stages of several cancers including KIRC, KIRP, LIHC and PAAD." (PMID 36059474, 2022). "New evidence suggests that RBX1 is a carcinogenic gene existing in several cancers, containing colon, liver, lung, ovarian, bladder, together with several other cancer cell lines." (PMID 35802537, 2022). "In accordance with the ubiquitination outcomes, degradation kinetic experiments reflected that in contrast to control cells, the exogenous FBXO45 half-life in the TNBC cancer cells overexpressing RBX1 was markedly lower." (PMID 35802537, 2022). "We performed a scale analysis of the expression of RBX1/2 from the TCGA database and found that they are highly expressed in most cancers." (PMID 36059474, 2022). "High expression levels of RBX1/2 were observed in most cancer types and correlated with poor prognosis of patients analyzed." (PMID 36059474, 2022). "Recent researches have exhibited that RBX1 not only exerts a critical role in modulating several cellular physiological functions, but is also participated in the cancer development." (PMID 35802537, 2022).